FLNA (filamin A)
Diseases named in the same sentence as FLNA in open-access papers (continued):
Sharing a sentence is not in itself a finding about the gene and the disease.
microcephaly (6 papers, 2015 to 2023). A congenital or acquired developmental disorder in which the circumference of the head is smaller than normal for the person's age and sex. "We have previously shown that actin-binding Filamin A (FlnA) and actin-nucleating Formin 2 (Fmn2) influence the development of the brain causing microcephaly in mice." (PMID 29240780, 2017). "Loss of both FlnA and Fmn2 result in impaired canonical Wnt signaling within neural progenitors by disrupting the trafficking of the Lrp6 receptor, thereby causing microcephaly (small brain)." (PMID 29240780, 2017). "As seen in the brain where loss of FlnA and Fmn2 leads to microcephaly due to impaired neural progenitor proliferation, a similar decrease in cell proliferation rates is observed in the thoracic wall and contributes to the phenotype." (PMID 29240780, 2017). "Only in one report has the mechanism been proposed in vivo, in filamin A knockout mice, which nevertheless displayed only a mild microcephaly phenotype due to a delay of cell division." (PMID 34571959, 2021). "However, double-KO mice of FMN2 and filamin A show greater microcephaly severity and less neural progenitor proliferation compared with the phenotype of single filamin A KO mice." (PMID 34685534, 2021). "While microcephaly is not seen in females with FLNA mutations (likely due to mosaicism), males die at birth and have been reported to have thinner cortices, and loss of cortical convolutions consistent with underlying microcephaly." (PMID 25883548, 2015).
neuroblastoma (6 papers, 2015 to 2025). Neuroblastoma (NB) is the most common solid, extracranial childhood tumor. "Increased expression of FLNA is associated with high-risk neuroblastoma tumors in patients, and inhibition of increased expression of FLNA by shRNA reduces xenograft neuroblastoma growth in mice." (PMID 39195282, 2024). "In high-risk neuroblastoma cell lines, transcriptional factor STAT3 interacts with FLNA, promoting tumor cell growth and phosphorylation and signaling." (PMID 39195282, 2024). "We confirmed the interaction of Tau with FLNA in neuroblastoma 2a (N2a) cells." (PMID 36399251, 2023).
pancreatic cancer (6 papers, 2013 to 2025). "ALDOA and PAF1 have recently been described as oncogenes in PDAC, whereas ENO1, RALGDS, TRIP10, and FLNA are known to mediate pancreatic cancer cell proliferation, survival and migration." (PMID 32029502, 2020). "Up-regulation of filamin-A was detected in salivary gland adenoid cystic carcinoma, peripheral cholangiocarcinomas, human glioblastomas and in pancreatic cancer." (PMID 23388158, 2013). "Moreover, Notch1 binding to PrPC, forming a complex with filamin A (FLNA), is necessary to sustain the proliferative and invasive phenotype of pancreatic carcinoma cell lines." (PMID 31752162, 2019). "Similarly, the expression of filamin-A was increased in pancreatic cancer, while in normal pancreas, exocrine ductal cells had low to moderate levels of filamin-A." (PMID 23388158, 2013).
bladder cancer (5 papers, 2019 to 2025). "All these findings suggested that ACTA2, FLNA, TAGLN and TPM1 were potential diagnostic biomarkers for bladder cancer." (PMID 37274283, 2023). "It has been demonstrated that the expression level of FLNA is significantly reduced in bladder cancer tissues and that FLNA overexpression can effectively inhibit the proliferation, invasion, and metastasis of bladder cancer cells, corroborating the results of the present study." (PMID 41181151, 2025). "The results of the analysis showed that seven genes (VCL, FLNA, THBS1, TAGLN, ACTA2, COL6A2, and CALD1) were significantly correlated (P < 0.05) with the prognosis of bladder cancer patients, and these genes were included in the subsequent in-depth study." (PMID 41181151, 2025). "Most disulfidoptosis genes were downregulated in multiple cancer types, including PDLIM1, TLN1, and MYH10 in lung squamous cell carcinoma (LUSC), MYL6 and DSTN in prostate adenocarcinoma (PRAD), and FLNA and ACTB in bladder cancer (BLCA)." (PMID 38862242, 2024). "Bioinformatic analyses demonstrated that the expression of ACTA2, FLNA, TAGLN and TPM1 in bladder cancer was markedly downregulated relative to nearby normal tissue." (PMID 37274283, 2023). "Next, we performed the survival analysis of these eight genes (ACTA2, CDH1, CCNB1, FLNA, MCM5, MAD2L1, TAGLN and TPM1) in bladder cancer." (PMID 37274283, 2023). "Finally, six B-cell marker genes (VCL, FLNA, TAGLN, ACTA2, COL6A2, and CALD1) that were downregulated in bladder cancer were screened using the PPI network, survival curves, ROC curve analysis, and expression validation." (PMID 41181151, 2025). "Overall, Alterations in the expression of VCL, FLNA, TAGLN, ACTA2, COL6A2, and CALD1 may play important roles in the development of bladder cancer, suggesting their potential value in early detection, molecular subtyping, and targeted therapy." (PMID 41181151, 2025). "By survival analysis, we found that their overall survival and disease-free survival curves also showed similarities, such as ACTA2 and TAGLN, FLNA and TPM1, suggesting that these genes have similar functions and are likely to be co-expressed and play a synergistic role in bladder cancer." (PMID 37274283, 2023). "Our study showed that FLNA expression was reduced in bladder cancer, but it was not clear whether this happened in the cytoplasm or the nucleus." (PMID 37274283, 2023).
COVID-19 (5 papers, 2020 to 2022). A disease caused by infection with severe acute respiratory syndrome coronavirus 2. "Two of the genes, MUC5AC and FLNA, have already been linked to the COVID-19 host response to different degrees." (PMID 34828448, 2021). "In this study, six co-upregulated genes, RPS7, IGF1R, DICER1, ERH, MCTS1, and TNPO1, and two co-downregulated genes, FLNA and PXN, were identified from COVID-19 and thrombosis datasets." (PMID 35692833, 2022). "Plasma protease C1 inhibitor was upregulated in COVID-19 patients, displaying a positive correlation, while FIBA, talin 1, filamin A, myosin heavy chain 9 and the beta subunit of hemoglobin, displayed negative correlations." (PMID 33096722, 2020). "Based on bioinformatics analysis and previous studies, this study identified hub genes (RPS7, IGF1R, DICER1, ERH, MCTS1, TNPO1, FLNA, and PXN) that may contribute to the evaluation and treatment of COVID-19 and thrombosis." (PMID 35692833, 2022).
fibrosarcoma (5 papers, 2009 to 2025). A malignant mesenchymal fibroblastic neoplasm affecting the soft tissue and bone. "Our findings subsequently showed that 10 nM androgens significantly enhance extra-nuclear association and co-localization of AR with the full-lenght FlnA in fibroblasts and fibrosarcoma-derived cells." (PMID 33500395, 2021). "At 10 nM concentration, the stapled peptide specifically disrupts the androgen-induced AR/FlnA complex assembly and motility in mouse and HNFs, as well as human fibrosarcoma-derived HT1080 cells." (PMID 33500395, 2021). "In other cancers such as lung, breast, squamous cell carcinoma, fibrosarcoma and glioma, cleavage and nuclear translocation of filamin A promotes metastatic transition with the propensity of filamin A to bind to growth factors and regulate their expression being key to this." (PMID 38958472, 2024). "To study the functions of FLNa we established HT-1080 human fibrosarcoma cell lines lacking FLNa expression." (PMID 19915675, 2009).
laryngeal squamous cell carcinoma (5 papers, 2019 to 2023). A squamous cell carcinoma that arises from the larynx. "More recent reports implicate Filamin-A (FLNA) expression in cell migration, progression, and prognosis of laryngeal squamous cell carcinoma (LSCC)." (PMID 37082492, 2023). "Circ_0092012 is originated from the exon 9 to 15 of the filamin A (FLNA) gene in chrX: 153592389–153594592, which was higher in laryngeal squamous cell carcinoma, and promoted cancer cell migration." (PMID 35723188, 2022). "Interestingly, a circRNA (circFLNA) derived from another filamin family gene, filamin A, was reported to impact the migration of the laryngeal squamous cell carcinoma, which is related histologically and anatomically to oral cancer." (PMID 32785098, 2020). "In laryngeal squamous cell carcinoma (LSCC), circFLNA functions in LSCC migration by sponging miR-486-3p which downregulate the FLNA protein expression." (PMID 34337069, 2021).
lung disease (5 papers, 2016 to 2025). "As well as neurological manifestations, other abnormalities, particularly cardiovascular symptoms and lung diseases, especially pulmonary hypertension, are also common in patients with FLNA mutations." (PMID 40735484, 2025). "Filamin A (FLNA) mutation is recently recognized to be associated with pediatric pulmonary disorders, however, the clinical courses of PAH related to the mutation were reported in limited cases." (PMID 33143682, 2020). "Among the broad range of diseases associated with FLNA mutation, lung diseases have been seen in most patients, such as pneumonia, and respiratory failure." (PMID 33143682, 2020). "We report the case of a male infant with a novel pathogenic variant of the FLNA gene mutation, who developed significant lung disease and in whom a periventricular nodular heterotopia was also diagnosed." (PMID 30922288, 2019). "In this study, we report a novel FLNA gene associated with significant lung disease and unique angiogenesis." (PMID 27091362, 2016). "In this case report, we describe another confirmatory mutation in the gene encoding filamin A (FLNA) in a female child with lung disease." (PMID 27091362, 2016). "In conclusion, we support the three previous reports in the literature, stating that there is an association between FLNA gene mutation and lung disease." (PMID 27091362, 2016). "Here, we report the case of a female child with a novel FLNA gene mutation who developed significant lung disease and unique angiogenesis." (PMID 27091362, 2016). "Our data support previous reports in the literature that associate FLNA gene mutation and lung disease." (PMID 27091362, 2016). "We report a novel variant of the FLNA gene, associated with a severe lung disorder and PNVH." (PMID 30922288, 2019). "FLNA mutations were recently found to be associated with lung disease." (PMID 27091362, 2016).
lymph node metastasis (5 papers, 2013 to 2024). "It was observed that the expression of the FLNa protein was associated with TNM stage, lymph node metastasis, vascular or neural invasion of the tumors, menstruation state and other risk stratifications (P<0.05)." (PMID 24137390, 2013). "tested samples of MPLC with lymph node metastasis (LNM) and found that the genes with the highest mutation frequencies in this pair were MUC16, FLNA, MUC4, FAT3, SETD2, and CALR, which implied that MPLC with LNM may have a unique mutation spectrum." (PMID 39411141, 2024). "Moreover, FLNA mRNA level was markedly higher in the lymph node metastasis group than in the group without lymph node metastasis." (PMID 31384171, 2019).
Macrothrombocytopenia (5 papers, 2013 to 2021). "Increased RhoA signaling through defective filamin A and αIIbβ3 interaction also underlies FLNA-linked macrothrombocytopenia." (PMID 34502272, 2021). "Notably, the macrothrombocytopenia phenotype found in RhoAfl/fl PF4CRE+ mice is similar to that found in mice with filamin A-null, GPIbα-null, GPIbβ-null, or Myh9-null megakaryocytes." (PMID 23935982, 2013). "Of these, ACTN1, which encodes alpha-actinin 1, was regarded as the most likely candidate by virtue of its functional role in the cytoskeleton and by analogy to some of the known macrothrombocytopenia genes, such as MYH9, FLNA and TUBB1." (PMID 24069336, 2013).
Marfan syndrome (5 papers, 2013 to 2023). A disorder of the connective tissue. "A recent proteomic analysis study using aortic medial tissue protein extract from Marfan Syndrome patients showed upregulation of the C-terminal fragmentation of filamin A, that was highly correlated with elevated calpain-2 activity." (PMID 23977256, 2013). "In support of this hypothesis, proteomics analysis of aortic media protein from Marfan syndrome patients showed increased fragmentation of filamin A protein with positive correlation of increased calpain activity." (PMID 23977256, 2013). "Although filamin A can be cleaved by caspase activity as well as granzyme B, proteomics analysis showed no alterations in activity of either caspase or granzyme B in the aortic media of Marfan syndrome patients." (PMID 23977256, 2013).
ovarian carcinoma (5 papers, 2019 to 2024). A malignant neoplasm originating from the surface ovarian epithelium. "Second, decreased expression of filamin A may be caused by transcriptional silencing of the FLNA gene through methylation, similarly to ovarian cancer, where relapse after chemotherapy is accompanied by hypermethylation of CpG islets in the promoter region of the FLNA gene." (PMID 34771736, 2021). "Among the identified proteins, significant enhanced expression of GFPT2, FLNA, TGFBI (CDGG1), ITGA2 predicted unfavorable prognosis in ovarian cancer patients." (PMID 36463238, 2022). "In the future, the precise roles of ASNS and FLNA in HGSC and LGSC remain to be elucidated, and additional cellular models of these ovarian cancer subtypes are needed." (PMID 31681605, 2019). "To investigate the roles of ASNS and FLNA in the behaviors of CS and CR ovarian cancer cells, we subjected CS cells to ASNS knockdown or FLNA overexpression and CR cells to ASNS overexpression or FLNA knockdown." (PMID 31681605, 2019). "Filamin A (FLNA) is a cytoskeletal protein and is possibly involved in the secretion of tissue factor-rich extracellular vesicles and DNA repair in tumors, including ovarian cancer with poor prognosis." (PMID 31681605, 2019).
pituitary tumor (5 papers, 2015 to 2022). A benign or malignant neoplasm affecting the pituitary gland. "The actin binding protein FLNA emerged as important player in the regulation of the complex intracellular processes that dictate pituitary tumors drug responsiveness and invasiveness." (PMID 33664708, 2020). "Recently, a role for cytoskeleton protein filamin A (FLNA) in DRD2 and SSTRs receptors expression and signaling in PRL- and GH-secreting tumors, respectively, has been demonstrated, first revealing a link between FLNA expression and responsiveness of pituitary tumors to pharmacological therapy." (PMID 26733942, 2015). "The cytoskeletal protein filamin A (FLNA) directly interacts with both somatostatin receptor type 2 (SST2) and 5 (SST5) and regulates their expression and signaling in pituitary tumoral cells." (PMID 35992099, 2022).
squamous cell carcinoma (5 papers, 2015 to 2024). A carcinoma arising from squamous epithelial cells. "Further investigation into potential mechanisms governing the effects of the MAPK-RSK-filamin A axis on cell migration in the A431 squamous carcinoma and DiFi colon cancer cell lines, characterised the pivotal role of α5β1 integrin in EGF stimulated cell migration." (PMID 38958472, 2024).
terminal osseous dysplasia (5 papers, 2014 to 2023). "Terminal osseous dysplasia with pigmentary defects (TODPD) is an X-linked dominant syndrome with distal limb anomalies, pigmentary skin defects, digital fibromas, and generalized bone involvement due to a recurrent mutation in the filamin A (FLNA) gene." (PMID 25614868, 2014).
glioma (4 papers, 2015 to 2024). A benign or malignant brain and spinal cord tumor that arises from glial cells (astrocytes, oligodendrocytes, ependymal cells). "FLNA was firstly shown to be associated with P311 protein, and colocalize on the leading edges of glioma cells." (PMID 26134617, 2015). "FLNA was a novel driver gene of tumor metastasis in GBM, and EIF3D was a protective gene for gliomas, of which high expression of EIF3D was related to an improved OS." (PMID 36233273, 2022).
oral cancer (4 papers, 2014 to 2023). "Loss of Filamin A, which is required for podosome stabilization during macrophage mesenchymal migration and localizes to podosomes in osteoclasts and to invadopodia in oral carcinoma cells, is associated with cleft palate in mice and in humans." (PMID 25259869, 2014). "Hence, it could be considered as a potential lead molecule for inhibiting protein filamin A in the treatment of oral cancer." (PMID 37720273, 2023). "Background and Aim: The genes ARRB1, FLNA, CALM3, and HTT are commonly expressed in oral cancer and have been hypothesized to be involved in the carcinogenic pathway." (PMID 33214751, 2020).
prostate tumor (4 papers, 2015 to 2024). "Targeting filamin A phosphorylation is another viable option to impede prostate tumour metastasis." (PMID 38958472, 2024). "In the potential interactors, FLNA has attracted our attention, which is a classical actin-crosslinking protein that stabilizes delicate three-dimensional actin networks during cell movements and has been identified as a regulator of Pi3k/Akt signaling in prostate tumors." (PMID 35957887, 2022). "Similarly, significantly lower mRNA expression of PMSA6 and FLNA, both down-regulated in DU145R80 cells, was detected in prostate tumor tissue vs normal tissue." (PMID 25481874, 2015).
acromegaly (3 papers, 2019 to 2024). Acromegaly is an acquired disorder related to excessive production of growth hormone (GH) and characterized by progressive somatic disfigurement (mainly involving the face and extremities) and systemic manifestations. "Tumor expression of particular genes was found of prognostic/predictive value in acromegaly patients, These genes include basically CDH1 and SSTR2 but also CDKN1B SNAI2, FLNA, ARRB1, SNAI1 RORC ESRP1, and MKI67." (PMID 39497133, 2024).
adenoma (3 papers, 2022 to 2025). A neoplasm arising from the epithelium. "Among these, APOA4, FERMT3, and FLNA exhibited consistent expression changes in the adenoma groups of both cohorts." (PMID 41367384, 2025). "Cytoplasmic expression of filamin A was statistically significantly higher in carcinomas compared to atypical adenomas or adenomas." (PMID 35805976, 2022). "Filamin A (FLNA) is poorly expressed in adrenocortical carcinomas (ACC) compared to adenomas (ACA)." (PMID 39528354, 2025). "Based on the consistency of their expression changes in the adenoma groups across both cohorts and their differential expression between inflammatory polyps and adenomas, we selected APOA4 and FLNA for further investigation, while excluding FERMT3 and THBS1." (PMID 41367384, 2025).
aortic aneurysm (3 papers, 2022 to 2025). A ruptured aneurysm located in the wall of the proximal portion of the descending aorta proceeding from the arch of the aorta. "Moreover, mutations in FLNA are known to cause aortic aneurysms." (PMID 40981182, 2025). "Many genes have been implicated in the etiology of non-syndromic aortic aneurysm such as ACTA2, MYH11, FLNA, and SMAD3." (PMID 38404628, 2023).
breast tumors (3 papers, 2018 to 2022). "The high expression of filamin A in breast tumor tissue may be associated with tumor promoting function." (PMID 29596499, 2018). "LAD1 was identified recently as an interactor of FLNA in mammary cells and may be a marker of aggressive breast tumors." (PMID 33266100, 2020). "Higher FLNA expression was detected in TNBC respect to luminal BC subgroup, whereas FLNB as well as FLNC expression levels were found higher in luminal breast tumors respect to TNBC." (PMID 35655319, 2022).
cleft palate (3 papers, 2014 to 2023). Cleft palate is a fissure type embryopathy that affects the soft and hard palate to varying degrees. "Specific to skeletal dysplasia, pathogenic variants in genes encoding type II and XI collagen (COL2A1, COL11A1 and COL11A2), Filamin-A (FLNA), and the diastrophic sulfate transport protein (SLC26A2) are all well-known as being associated with cleft palate." (PMID 33446226, 2021).